SLC26A9 (solute carrier family 26 member 9)
Diseases named in the same sentence as SLC26A9 in open-access papers (continued):
Sharing a sentence is not in itself a finding about the gene and the disease.
bile reflux (1 paper, 2023). "At present, several factors including H.Pylori (Hp), flora imbalance, inflammatory factors, genetic variations, Claudin-4, gastric stem cells, solute carrier family member 26 (SLC26A9), bile reflux, exosomes, and miR-30a plays a considerable role in the transformation of GPL into GC." (PMID 37719006, 2023).
blood pressure (1 paper, 2015). "However, the study of Slc26a9 in a renal transport physiology group indicated not only an expression of Scl26a9 in specialized cells of the collecting duct but also a reduction of renal Cl- excretion and high blood pressure in Slc26a9-deficient mice." (PMID 24965066, 2015).
chronic atrophic gastritis (1 paper, 2022). Atrophic gastritis that is persistent and long-standing. "By 14 months of age, all of the Slc26a9-deficient mice (23/23) exhibited a severe gastric preneoplastic phenotype, including chronic atrophic gastritis (CAG), mucous cell metaplasia, profound cyst formation and high-grade intraepithelial neoplasia (HGIN), equivalent to early GC." (PMID 35426084, 2022). "Analysis of human gastric precancerous and cancerous tissues revealed that SLC26A9 expression progressively decreased from atrophic gastritis to GC, and that downregulation of SLC26A9 was correlated with patient survival." (PMID 35426084, 2022). "In human gastric mucosal specimens of various pathologies, we found that SLC26A9 expression decreased progressively from chronic atrophic gastritis to GC." (PMID 35426084, 2022).
chronic obstructive pulmonary disease (1 paper, 2022). A chronic and progressive lung disorder characterized by the loss of elasticity of the bronchial tree and the air sacs, destruction of the air sacs wall, thickening of the bronchial wall, and mucous accumulation in the bronchial tree. "We investigate the relationship between rs7512462, a marker of SLC26A9 activity, and lung function pre- and post-treatment with CFTR modulators in Canadian and US CF cohorts, in the general population, and in those with chronic obstructive pulmonary disease (COPD)." (PMID 35396391, 2022).
COVID-19 (1 paper, 2022). A disease caused by infection with severe acute respiratory syndrome coronavirus 2. "Among the rare variants extracted, we identified some genes as candidates for COVID-19 severity, including TLR5 and SLC26A9 as well as other genes involved in the inflammatory response." (PMID 34889978, 2022).
cystic fibrosis-related diabetes (1 paper, 2023). Cystic fibrosis-related diabetes is a form of diabetes that occurs frequently in individuals with cystic fibrosis. "Additional genes implicated in the development of cystic fibrosis-related diabetes (CFRD) include PM20d1, which is located near the SLC26A9 gene, and PTMA." (PMID 37893045, 2023).
duodenal ulcer (1 paper, 2018). An ulcer in the duodenal wall. "Although most studies have focused on the role of Slc26a9 in CF-related disease onset, we anticipate that Slc26a9 may also be involved in the pathogenesis of some unreported diseases, such as duodenal ulcers, Type 2 diabetes and hypertension, based on functional analysis." (PMID 30233393, 2018).
dysplasia (1 paper, 2022). A usually neoplastic transformation of the cell, associated with altered architectural tissue patterns. "We found that slc26a9−/− mice displayed histopathologic and molecular features from atrophy, metaplasia, mucosal barrier defects, and dysplasia to intraepithelial neoplasia over the lifespan of the mice." (PMID 35426084, 2022).
esophageal adenocarcinoma (1 paper, 2021). A malignant tumor with glandular differentiation arising predominantly from Barrett mucosa in the lower third of the esophagus. "Transcriptomics showed that the combination of SLC26A9 and the other four genes, SINHCAF, MICB, KRT19, and MT1X, became a gene signature that predicts the overall survival of esophageal adenocarcinoma." (PMID 35008199, 2021). "The combination of SLC26A9 with AP002478.1, BHLHA15, FFAR2, IGFBP1, KCTD8, and PHYHD1 was also identified as a gene signature for personalized prognosis prediction and targeted therapy of esophageal adenocarcinoma." (PMID 35008199, 2021).
Gastric Metaplasia (1 paper, 2022). Intestinal metaplasia of the gastric mucosa is an intermediate precancerous gastric lesion in the gastric cancer cascade from chronic gastritis and atrophy to dysplasia and adenocarcinoma. "Our data indicate that SLC26A9 deletion in parietal cells is sufficient to trigger gastric metaplasia and the development of neoplastic lesions." (PMID 35426084, 2022).
kidney stone (1 paper, 2023). "Moreover, SLC45A3 and SLC26A9 were involved in the biological process of ion transport and pH regulation, which was crucial to kidney stone formation." (PMID 37980427, 2023).
lung carcinoma (1 paper, 2025). "Although mechanistic studies on the role of SLC26A9 in TNBC CSC regulation are still in their early stages, existing research has suggested that SLC26A9 plays important roles in various solid tumors, such as lung cancer." (PMID 41323464, 2025).
pancreatic cancer (1 paper, 2007). "We used T-84 cells, a human colonic cell line, as a positive control for SLC26A3, and Capan-1 cells, a metastatic human pancreatic cancer cell line, for SLC26A9." (PMID 17635413, 2007).
Sjögren’s syndrome (1 paper, 2018). "Recently, dysfunction of Slc26a9-mediated ion composition was associated with Sjögren’s syndrome (SS) onset, according to the alteration of the expression and cellular localization of Slc26a9 in SS saliva when compared with healthy controls." (PMID 30233393, 2018).
thyroid disease (1 paper, 2021). "Cotransporter genes involved in achlorhydria (SLC26A7, SLC26A9 and ATP4A) were also strongly associated with thyroid disease in thyrogastric patients, suggesting a monogenic model for the thyrogastric syndrome." (PMID 34944008, 2021).
Type 2 diabetes (1 paper, 2018). "Thus, Slc26a9 can function as an alternative chloride channel to regulate fluid absorption and glucose metabolism in the pancreas, suggesting that Slc26a9 may not only be involved in CF-related diabetes (CFRD) onset but also may contribute to the occurrence of Type 2 diabetes." (PMID 30233393, 2018).
cancer (7 papers, 2019 to 2025). A tumor composed of atypical neoplastic, often pleomorphic cells that invade other tissues. "Additionally, existing studies have validated the role of SLC26A9 in different types of cancer cells through in vitro experiments." (PMID 41323464, 2025). "In the context of cancer stem cells (CSCs), the role of SLC26A9 has attracted increasing attention." (PMID 41323464, 2025). "Conversely, downregulated Cl− recycling and increased pHi levels may explain the malignant behavior in cancer cells with downregulated Slc26a9 and AE2 expression." (PMID 35426084, 2022). "The overall results suggest that SLC26A9 inhibits the proliferation and migration of HNSC cells, highlighting its therapeutic potential as a target for addressing this type of cancer." (PMID 38913914, 2024). "Similar to the clinical specimens, we found that nonmalignant and well-differentiated carcinoma cells exhibited a higher SLC26A9 expression than nondifferentiated carcinoma cells." (PMID 35426084, 2022). "Nevertheless, information regarding the role of SLC26A9 in cancer is lacking." (PMID 34234806, 2021). "SLC26A9 is predominantly down-regulated in cancer, and has no change in NPCs." (PMID 31071451, 2019). "However, the role of SLC26A9 in cancer has not yet been elucidated." (PMID 35008199, 2021).
tumor (6 papers, 2021 to 2025). "Among the enriched terms, the Notch signaling pathway emerges as a key axis that connects SLC26A9 with stemness maintenance and tumor progression." (PMID 41323464, 2025). "Beyond maintaining intracellular and extracellular ion homeostasis, cellular polarity, and pH balance, SLC26A9 directly participates in signal transduction and adapts to the tumor microenvironment." (PMID 41323464, 2025). "After quantification of SLC26A9 protein expression in the tumor and adjacent normal tissues, the patient population was sorted based on SLC26A9 expression above (SLC26A9 high) or below (SLC26A9 low) the median." (PMID 35426084, 2022). "Based on the changes in the expression levels of genes in EBV-infected cell lines and tumor tissues, we identified two upregulated genes, SLC26A9 and TMC8, as gene signatures for EBVaCAs." (PMID 35008199, 2021). "Next, we surveyed the impact of SLC26A9 on neoplasm growth in vivo." (PMID 38461207, 2024). "In addition, the ROC curve indicates that SLC26A9 can be used to diagnose and monitor the clinical treatment effect and has potential clinical significance as a tumor marker." (PMID 38461207, 2024). "Two genes, SLC26A9 and TMC8, were identified as gene signatures for EBVaCAs because these two genes were upregulated in all EBV-positive cell lines and tumor tissues." (PMID 35008199, 2021). "Therefore, we detected the expression of SLC26A9 in clinical CRC samples by Immunohistochemistry (IHC) and western blot (WB) and revealed the effects of SLC26A9 on the biological behavior of CRC cells in vitro and tumor growth in vivo." (PMID 38461207, 2024). "In contrast, SLC26A9 silencing promoted the apoptosis of human CRC cells but inhibited their migratory functions in vitro and reduced tumor growth in vivo, suggesting that SLC26A9 may have a proliferative and migratory promoting effect during CRC progression." (PMID 38461207, 2024). "In addition, downregulation of SLC26A9 in CRC cells induced cell cycle arrest and apoptosis but inhibited cell proliferation and xenograft tumor growth both in vitro and in vivo." (PMID 38461207, 2024). "SLC26A9 overexpression was associated with T stage (p < 0.05), lymph node metastasis (p < 0.05), distant metastasis (p < 0.01), TNM stage (p < 0.05), and Duke stage of CRC but was not correlated with age, sex or tumor size." (PMID 38461207, 2024). "Therefore, we further confirmed whether the upregulated BAMBI, SLC26A9, SGPP2, and TMC8 genes could be used as a gene signature for EBVaCAs by determining the expression levels of these four genes in cell lines and tumor tissues by qRT-PCR." (PMID 35008199, 2021). "Similarly, the expression of SLC26A9 and TMC8, but not BAMBI or SGPP2, was significantly upregulated in EBV-positive tumor tissues compared with that in EBV-negative tumor tissues." (PMID 35008199, 2021). "However, SLC26A9 and TMC8, but not BAMBI and SGPP2, were significantly upregulated in EBV-positive tumor tissues compared to EBV-negative tumor tissues." (PMID 35008199, 2021).
renal disease (2 papers, 2017 to 2023). "The Cl−-transporting proteins CFTR, SLC26A9, and anoctamin (ANO1; ANO6) appear to have more in common than initially suspected, as they all participate in the pathogenic process and clinical outcomes of airway and renal diseases." (PMID 37686084, 2023).
respiratory disorders (1 paper, 2021). "The exact direct role that SLC26A9 plays in CF and in other respiratory disorders is, however, yet to be elucidated." (PMID 34884866, 2021).
SLC26A9 also shares sentences with these, for which no sentence is quoted: adenocarcinoma (1 paper); cardiovascular disease (1); chronic lung disease (1); chronic pancreatitis (1); colorectal adenocarcinoma (1); cyst (1); exocrine pancreatic insufficiency (1); Gastric Neuroendocrine Tumors (1); Hypertension (1); infection (1); intraepithelial neoplasia (1); osteoporosis (1); pancreatic disease (1); pancreatitis (1); Peptic ulcer (1); signet ring carcinoma (1); triple-negative breast carcinoma (1).